ADM (adrenomedullin)
Diseases named in the same sentence as ADM in open-access papers (continued):
Sharing a sentence is not in itself a finding about the gene and the disease.
Sepsis (continued). "For understanding the controversial effects of adrenomedullin on endothelial barrier function and survival of sepsis that have been observed over the past decades, the distribution of adrenomedullin between the circulation and interstitium is crucial." (PMID 35741064, 2022). "These peptides have different biological functions, but some share some similarities with PCT, like its possible increase in sepsis, such as adrenomedullin and calcitonin." (PMID 35428339, 2022). "Other biomarkers such as preseptin or pro-adrenomedullin (pro-ADM) have also been postulated as promising biomarkers in sepsis." (PMID 36459524, 2022). "The performance of adrenomedullin to quantify infection in children seems satisfactory, especially in sepsis." (PMID 36010070, 2022). "There is already initial clinical data announced on the blockade of adrenomedullin in sepsis, which raises hopes at least for this indication." (PMID 36362673, 2022). "In the second approach, a humanized ADM-binding antibody (Adrecizumab, HAM8101) was shown to increase plasma ADM levels and reduce systemic inflammation and endotoxin-induced flu-like symptoms in sepsis models." (PMID 36362188, 2022). "Elevated levels of ADM representing endothelial damage and microvascular alteration have been found in patients with sepsis and organ dysfunctions such as heart and respiratory failure." (PMID 36016305, 2022). "Mid-Regional pro-Adrenomedullin (MR-proADM) is an inflammatory biomarker that improves the prognostic assessment of patients with sepsis, septic shock and organ failure." (PMID 36031619, 2022). "Adrenomedullin (ADM) is also elevated in sepsis, which results in pro-ADM that is present at higher levels in patients with localized infections and bacteremia than in healthy controls." (PMID 33869250, 2021). "We describe the general vascular properties of DPP3 and ADM and provide an overview of the current understanding of the different roles of these molecules in sepsis and septic shock." (PMID 33381880, 2021). "Adrecizumab (HAM8101) is an anti-adrenomedullin (anti-ADM) antibody that targets vascular and capillary leakage in sepsis and inflammation and ultimately stabilizes and maintains endothelial barrier function." (PMID 34945800, 2021). "Given the availability of rapid bedside biomarker assays for both DPP3 and ADM, they represent promising opportunities for the conduct of biomarker‐guided sepsis trials." (PMID 33381880, 2021). "In this review, we focus on dipeptidyl peptidase 3 (DPP3) and adrenomedullin (ADM), two molecules that act on the vasculature and are involved in the pathophysiology of sepsis and septic shock." (PMID 33381880, 2021). "Pro-ADM has shown to be more suggestive of sepsis than PCT in cancer patients, and its levels are more significantly elevated in patients with hematological cancers and localized infections than in those with no infections." (PMID 33869250, 2021). "AMBP is a plasma protein that binds adrenomedullin and acts as an important modulator in the biphasic septic response, including during the progression of polymicrobial sepsis." (PMID 32411128, 2020). "Adrenomedullin is a vasoactive hormone, with reported prognostic and potentially therapeutic value in sepsis." (PMID 33148300, 2020). "Despite that the level of serum ADM increases in the body during pneumonia, sepsis and cardiac disease, the highest increase is observed during pregnancy." (PMID 32025333, 2020). "Previous research found increased ADM plasma levels in patients with sepsis and ADM levels correlated with disease severity and mortality in sepsis." (PMID 32859259, 2020). "Preclinical studies have demonstrated that the use of antibodies that bind to the N-terminus of ADM results in an overall increase of circulating ADM levels and improves sepsis outcome." (PMID 29520277, 2018). "Overview of preclinical studies with ADM antibodies and/or antagonists in different models related to sepsis." (PMID 29520277, 2018).
Sepsis (continued). "Adrenomedullin (ADM), a free circulating peptide involved in regulation of endothelial barrier function and vascular tone, is implicated in the pathophysiology of sepsis." (PMID 29520277, 2018). "In sepsis patients, circulating ADM levels correlated with relaxation of vascular tone as well as with disease severity and mortality." (PMID 29520277, 2018). "It has been shown that, in sepsis, the gut releases, among other substances, adrenomedullin, a potent vasodilatory peptide." (PMID 28499395, 2017). "As early as 1996, Hirata and colleagues showed that levels of ADM increased with disease severity in adults with sepsis." (PMID 28702296, 2016). "In sepsis there is upregulation of ADM expression and ADM seems to be important for the initiation and continuation of hyperdynamic shock in animal models." (PMID 27282767, 2016). "Adrenomedullin (ADM) plays a central role in initiating the hyperdynamic response during the early stages of sepsis." (PMID 24533868, 2014). "Adrenomedullin (ADM) is a peptide first isolated from a human pheochromocytoma, and has been found to be elevated in plasma of sepsis patients." (PMID 24533868, 2014). "Our study aimed to explore the clinical utility of basal and serial plasma ADM assessments in patients hospitalized for sepsis using this new assay." (PMID 24533868, 2014). "Caution is therefore mandatory with the development of adrenomedullin as a drug, as with any new treatment for sepsis." (PMID 25041977, 2014). "Since adrenomedullin is a strong vasodilatory molecule, further studies are needed to evaluate its potential as a future treatment of sepsis." (PMID 25041977, 2014). "In the present study we demonstrated a strong association of admission ADM levels with the severity of the disease, supporting an earlier report describing elevated ADM levels in those with severe sepsis and those with septic shock." (PMID 24533868, 2014). "The anti-mouse ADM antibodies were tested in a CLP sepsis mouse model for their ability to reduce mortality." (PMID 26266791, 2013). "It has been known that plasma ADM levels strongly increase with the severity of sepsis, severe sepsis, and septic shock, and that elevated levels are highly prognostic for fatal outcome." (PMID 26266791, 2013). "Adrenomedullin is a member of the calcitonin peptide superfamily, and is a reliable early prognostic marker of sepsis in humans, with a prognostic accuracy similar to the APACHEII score and procalcitonin expression." (PMID 23009705, 2012). "In conclusion, baseline endothelin-1 and adrenomedullin precursor levels are significantly increased in patients with sepsis and septic shock." (PMID 18080871, 2007). "Endothelin-1 (ET-1) and adrenomedullin (ADM), two endothelium-derived vasoactive peptides, have attracted interest as physiological key mediators in vascular tone regulation in sepsis and cardiovascular disease." (PMID 18080871, 2007). "Firstly, as a member of the calcitonin gene family, ADM is widely expressed and extensively synthesized during severe infections, that is, sepsis, similar to other calcitonin peptides, namely procalcitonin and calcitonin-gene related peptides." (PMID 16805922, 2006). "First, as a member of the CALC gene family, ADM is widely expressed and extensively synthesized during sepsis, similar to other calcitonin peptides including PCT and calcitonin-gene related peptides." (PMID 16356231, 2005). "The median concentration of ADM-Gly was significantly elevated in patients with sepsis (121.5 pg/mL [IQR: 44.4–284.1 pg/mL]; p < 0.0001) and septic shock (419.3 pg/mL [IQR: 148.8–1106 pg/mL]; p < 0.0001), when compared to the self-reported healthy individuals (17.5 pg/mL [IQR: 11.5–27.2 pg/mL])." (PMID 40993326, 2025). "Adrenomedullin (ADM), a naturally occurring hormone with a potent vasodilatory effect, has emerged as a potential biomarker to aid in the diagnosis and prognostication of sepsis and septic shock in humans." (PMID 39518777, 2024).
Sepsis (continued). "Plasma bio-ADM concentrations were significantly higher in both septic groups compared to the healthy controls (all <22.4 pg/mL), but not significantly different between the septic shock (75.0 [28.7–115.0] pg/mL) and sepsis (30.7 [22.4–79.7] pg/mL) groups." (PMID 39518777, 2024). "Adrenomedullin (ADM) is a small peptide hormone secreted by various tissues, including vascular smooth muscle cells and endothelium, particularly in pathological conditions such as sepsis." (PMID 39414666, 2024). "Within the realm of biomarkers that reflect endothelial dysfunction, we might focus on adrenomedullin (ADM), which is a vasoactive hormone, with reported prognostic and potentially therapeutic value in sepsis." (PMID 39211340, 2024). "In terms of inflammatory biomarkers, procalcitonin (17.5 ng/mL vs. 8.4 ng/mL; p = 0.01) and ferritin (1096 μg/L vs. 944 μg/L; p = 0.001) were higher in sepsis, while fibrinogen (6.4 g/L vs. 4.6 g/L; p = 0.001) and adrenomedullin (1.72 nmol/L vs. 1.47 nmol/L; p = 0.01) were higher in MIS-C." (PMID 37676491, 2023). "In these situations, biomarkers like IGFBP-2 or mid-regional pro-adrenomedullin levels (MR-proADM) could confirm sepsis." (PMID 38137505, 2023). "The link between high levels of adrenomedullin and mortality has previously been shown for sepsis and may be due to marked vasodilation and hypotension." (PMID 36864354, 2023). "Clinicians can now rely on several serum biomarkers for the diagnosis of sepsis (e.g., procalcitonin), and promising new biomarkers have been evaluated, e.g., presepsin and adrenomedullin, although their clinical relevance in the hospital setting is still under discussion." (PMID 35741168, 2022). "When ADM was correlated with the C-reactive protein levels in these patients, it could identify sepsis or cancer patients." (PMID 36004964, 2022). "By increasing the functional plasma ADM levels, Adrecizumab is hypothesized to target the sepsis- and inflammation-based vascular and capillary leakage." (PMID 32796765, 2020). "In adrenals, where ADM was first described, sepsis decreased ADM and CRLR expression." (PMID 31093784, 2019). "Given the role of ADM in vasodilation and capillary leakage, the objective of this work was to explore the haemodynamic, inflammatory, and myocardial oxidative stress responses to therapeutic treatment with Adrecizumab, which induced partial inhibition of ADM, in a sepsis model in rats." (PMID 31093784, 2019). "In a mouse model of sepsis (caecal ligation and puncture, CLP), preventive treatment by Adrecizumab increased survival, while other antibodies directed against different epitopes of ADM (causing greater or complete inhibition of ADM signalling) did not." (PMID 31093784, 2019). "Adrenomedullin is an important peptide hormone involved in sepsis." (PMID 29520277, 2018). "However, the pro-ADM levels in previous studies were analyzed during the course of sepsis due to respiratory, urinary tract, or abdominal infections, but not CRBSI as evaluated in the present study." (PMID 30334979, 2018). "Furthermore, next to effects on vascular tone and the endothelial barrier, ADM also has other properties relevant in the context of sepsis, including immunoregulatory, antimicrobial and cardioprotective effects." (PMID 29520277, 2018). "Proadrenomedullin (pro-ADM) has emerged as a valuable marker of sepsis." (PMID 30334979, 2018). "In our study we found that adrenomedullin levels at ED admission were much higher in patients who progressed toward severe sepsis or septic shock, showing a similar predictive significance as compared to PSI and CURB65, thus representing an additional and easy-to-determine prognostic tool." (PMID 29161297, 2017). "In summary, previous work has established that high endogenous levels of ADM correlate with poor outcomes and that exogenous administration improved outcomes, while now it is reported that antagonism of ADM using antibodies improves outcome in an animal sepsis model." (PMID 26266901, 2014).
Sepsis (continued). "In the previous issue of Critical Care, Müller-Redetzky and colleagues propose that adrenomedullin may be promising to treat sepsis." (PMID 25041977, 2014). "Previously, the CRLR ligand adrenomedullin ameliorated inflammatory responses in polymicrobial sepsis suggesting that CRLR signalling may mediate immunomodulating effects." (PMID 22563471, 2012). "Besides being a potent vasodilating agent, adrenomedullin is an immune-modulating and antibacterial mediator and a potential therapeutic target for sepsis." (PMID 23009705, 2012). "Similarly, the vasoactive hormone adrenomedullin has been shown to be beneficial in sepsis by abrogating the progression to irreversible shock." (PMID 22481914, 2012). "In our mouse model of sepsis, adrenomedullin was significantly up-regulated at the early time points (DE 3.95 and 5.03 at 1 and 2 h, respectively) while it was down-regulated at 18 h (DE −1.95) which corresponds with the recovery from sepsis." (PMID 23009705, 2012). "In addition to its vasodilatory function, adrenomedullin decreases cytokines in the circulation of septic animals what synergistically protects animals from dying of sepsis." (PMID 22481914, 2012). "As the kidneys are commonly affected in sepsis and adrenomedullin is also produced in the kidneys, in particular in hypoxic conditions, this might be an early sign of renal damage and a possible host response to counteract renal tissue damage by increasing renal blood flow and thus diuresis." (PMID 40447978, 2025). "The investigators hypothesised that partial functional inhibition of ADM negates the harmful effects of excessive ADM while still preserving an adequate degree of ADM activity which may be required, especially in the early hyperdynamic phase of sepsis." (PMID 38521954, 2024). "Some studies have suggested that sepsis onset could lead to immune system cell damage and endotheliitis, resulting in biohumoral dysregulation, inflammation with oxidative stress and the increased expression of adrenomedullin (ADM)." (PMID 38139258, 2023). "However, there have been issues hampering the transfer to bedside of adrenomedullin in sepsis." (PMID 35741064, 2022). "Conversely, adrenomedullin infusion reduced endothelial permeability and increased survival in preclinical animal models of sepsis, indicating that adrenomedullin may be a double-edged sword in modulating the host response during sepsis." (PMID 35741064, 2022). "Adrenomedullin present in the circulation protects vascular barrier function in sepsis, whereas adrenomedullin in the interstitium leads to vasodilatation and impairs vascular barrier function, which has become clear when using an antibody inducing a shift of adrenomedullin into the circulation." (PMID 35741064, 2022). "In addition, plasma levels of adrenomedullin, a free circulating peptide involved in the regulation of endothelial barrier function and vascular tone, were found to be increased in sepsis and to correlate with the extent of vasodilation as well as with disease severity and mortality." (PMID 33670874, 2021). "Therefore, modulation of ADM activity could have therapeutic potential during sepsis to restore haemodynamics and improve clinical outcome." (PMID 31093784, 2019). "Moreover, it was reported that lung injury owing to sepsis might impair the removal of circulating ADM, which also may contribute to an increase of pro-ADM level." (PMID 30334979, 2018). "Thus, ADM is considered a “hormokine”, characterized by a hormone-like behaviour in non-inflammatory conditions when it is only produced by endocrine cells, and by a cytokine-like behaviour in sepsis when it is ubiquitously hyper-expressed." (PMID 28185230, 2017). "In addition, polymicrobial sepsis may induce further processes like adrenomedullin or kynurenine expression, which by themselves downregulate systemic blood pressure." (PMID 23935245, 2013).
Sepsis (continued). "Hence, even in sepsis, circulating levels of ADM are only modestly elevated, and are not significantly different between patients with systemic inflammatory response syndrome and patients with sepsis, prohibiting its use as a diagnostic and prognostic tool." (PMID 16805922, 2006). "Median bio-ADM levels were 40 pg/mL in the entire ICU cohort, 74 pg/mL in patients with sepsis, 107 pg/mL in patients with septic shock, and 29 pg/mL in non-septic patients." (PMID 40572747, 2025). "The aim of this narrative review is to provide insight into the role of two novel biomarkers, namely adrenomedullin (ADM) and dipeptidyl peptidase 3 (DPP3), in sepsis." (PMID 40572747, 2025). "Biologically active adrenomedullin (Bio-ADM) is an emerging biomarker of endothelial function and vascular integrity already proven to be of utility in patients with sepsis in the ED." (PMID 36557054, 2022). "Further, antagonizing the N-terminal side of adrenomedullin with the antibody HAM1101 improved responsiveness to vasopressors and kidney function in murine sepsis." (PMID 35741064, 2022). "Like adrenomedullin, procalcitonin (PCT) belongs to the calcitonin peptide family and is used as an early and predictive sepsis biomarker." (PMID 35741064, 2022). "In healthy states, peptide hormones such as adrenomedullin (ADM) stabilize and regulate the endothelial barrier, but are disturbed in sepsis and septic shock." (PMID 36233650, 2022). "Several studies showed that plasma ADM values increased in patients with hypertension, heart failure, AMI, pulmonary hypertension, and sepsis and suggest that ADM was a marker of endothelial function." (PMID 34640526, 2021). "In two studies, combining a sepsis biomarker with a severity score improved the predictive value (urokinase plasminogen activator receptor [uPAR] + APACHE II AUC, 0.83; adrenomedullin + Mortality in Emergency Department Sepsis (MEDS) score AUC, 0.81)." (PMID 32503670, 2020). "Adrecizumab (HAM8101) is a first-in-class humanized monoclonal anti-Adrenomedullin (anti-ADM) antibody, targeting the sepsis- and inflammation-based vascular and capillary leakage." (PMID 32796765, 2020). "Adrenomedullin (ADM), a 52 amino acid peptide hormone, has been proposed as a pivotal mediator of vascular dysfunction in sepsis." (PMID 31093784, 2019). "Adrenomedullin (ADM) is a potent vasodilating peptide which is widely expressed and synthesized during sepsis." (PMID 30154872, 2018). "Adrenomedullin (ADM) plays an important role in the inflammation process and in progression from sepsis to septic shock." (PMID 30177659, 2018). "We aimed to evaluate the diagnostic value of neutrophil-to-lymphocyte count ratio (NLCR), neopterin, pro-adrenomedullin (pro-ADM) and the other infection markers to predict bacteremia in patients with SIRS, sepsis and severe sepsis/septic shock." (PMID 30559815, 2018). "Several clinical studies have demonstrated that ADM, ANP, and BNP are predictors of adverse outcome in patients with sepsis, but most of these studies were conducted in the ICU and contained relatively small sample sizes." (PMID 26880865, 2016). "Among innovative biomarkers, pro-adrenomedullin (pro-ADM), particularly its stable fragment mid-regional pro-adrenomedullin (MR-proADM), has shown promise for detecting endothelial dysfunction and predicting organ failure in sepsis." (PMID 41096721, 2025). "Notably, CALCRL downregulation in sepsis disrupts its interaction with RAMP2/3 (receptor activity-modifying proteins), thereby impairing adrenomedullin clearance and compromising its protective anti-inflammatory functions." (PMID 40761792, 2025). "In the analysis of the studies on PCT's role in the diagnosis of sepsis, three studies compared PCT's role and utility to other biomarkers, such as lactate, presepsin, and mid-regional pro-Adrenomedullin (MR-proADM), in the diagnosis of sepsis in the emergency department." (PMID 38254218, 2024).